ATRX (ATRX chromatin remodeler)
Diseases named in the same sentence as ATRX in open-access papers (continued):
Sharing a sentence is not in itself a finding about the gene and the disease.
glioma (continued). "In another study, ATRX expression and loss of 1p/19q were simultaneously observed in only 3 of 1.041 glial tumors." (PMID 30592195, 2019). "Loss-of-function mutations in ATRX likely play central pathogenic roles in several distinct tumor variants, including multiple subtypes of incurable glioma." (PMID 30808951, 2019). "Predicted glioma drivers associated with chromatin organization include ATRX, SETD2, ARID2, DNMT3A, SMARCA4, and ARID1A." (PMID 30644073, 2019). "It has been shown, that ATRX loss in glioma grade II and III tumors, is an alternative way of telomere elongation, alternative to telomerase reverse transcriptase (TERT) promoter mutations." (PMID 31311166, 2019). "ATRX deficiency almost invariably co-occurs with mutations in IDH1 or its homologue IDH2 in adult gliomas." (PMID 30808951, 2019). "Our findings reveal novel pathogenic mechanisms driven by ATRX deficiency in glioma, while also pointing to tangible strategies for drug development." (PMID 30808951, 2019). "Taken together, these in vivo findings further support the therapeutic potential for chemical G4 stabilization in the selective targeting of ATRX-deficient glioma." (PMID 30808951, 2019). "To model the genomic consequences of ATRX deficiency in a glioma-relevant cellular context, we performed shRNA-mediated ATRX knockdown in TERT and E6/E7-transformed NHAs." (PMID 30808951, 2019). "Due to its sheer prevalence in glioma, ATRX deficiency represents a molecular target of intriguing therapeutic potential." (PMID 30808951, 2019). "Some molecular genetic features including IDH1/2 mutation, MGMT promoter methylation, co-deletion of 1p/19q, TERT loss, and ATRX mutation have been reported to be associated with favorable prognosis in gliomas." (PMID 30658672, 2019). "This was supported by the previous studies that glioma patients with LGGs and ATRX mutations generally had better prognosis than those with GBMs and wild-type ATRX18." (PMID 30936423, 2019). "Patients with IDH1 mutations are thought to comprise secondary GBM as they are enriched for ATRX mutations similar to that found in lower-grade glioma and patients survive for a median survival of 31 months which is consistent with lower-grade glioma." (PMID 30778375, 2019). "In this study, we have examined the effects of ATRX loss on the ALT telomere maintenance mechanism in telomerase-positive human glioma cell lines." (PMID 30226859, 2018). "To investigate this possibility, we re-engineered the basic molecular features of ATRX-deficient glioma in a disease-relevant cellular context." (PMID 29535300, 2018). "For example 66% of pancreatic cancer cases and 40% of gliomas with a mosaic staining pattern had an identifiable ATRX mutation identified by next-generation sequencing." (PMID 29796169, 2018). "In order to assess the effects of ATRX loss on ALT in glioma cell lines, we sought to generate clonal cell lines with functional knockout of ATRX in these seven cell lines." (PMID 30226859, 2018). "That being said, our validation studies in ATRX-deficient human gliomas suggest that the cell migratory and differentiation phenotypes identified in our mNPC models are driven primarily by ATRX loss." (PMID 29535300, 2018). "Contrary to adult IDH-wildtype diffuse glioma, H3-mutant malignant pediatric glioma frequently demonstrates ALT, and several studies reported frequent co-occurrence of ATRX mutations in both H3 K27 and G34 mutant gliomas." (PMID 29616301, 2018). "Mutational inactivation of the SWI/SNF chromatin regulator ATRX occurs frequently in gliomas, the most common primary brain tumors." (PMID 29535300, 2018).
glioma (continued). "In a larger sense, they also suggest that functionally relevant epigenetic and transcriptional alterations mobilized by Atrx deficiency in murine mNPCs are also operative in ATRX-mutant human gliomas." (PMID 29535300, 2018). "That virtually all IDH-mutant adult gliomas feature either ATRX deficiency or activating mutations in TERT2, which encodes the catalytic core of telomerase, speaks to the absolute necessity of pathological telomere maintenance across the tumor group." (PMID 29535300, 2018). "Particularly robust associations were found with early progenitor-like (EPL), LGG R1, and LGG R3 signatures, all of which are derived from glioma subclasses featuring high rates of ATRX mutation." (PMID 29535300, 2018). "Taken together, our results demonstrate that ATRX deficiency drives glioma-relevant biology by directly modulating chromatin architecture and composition, thereby influencing the expression of phenotypically crucial gene sets." (PMID 29535300, 2018). "In order to assess the telomere-associated effects of ATRX loss, we chose a glioma in vitro model system, due to the relatively high frequency of ATRX loss and ALT in glioma." (PMID 30226859, 2018). "Further study will help clarify the link between partial ATRX loss in gliomas with the presence of ALT in order to more effectively use ATRX as a surrogate marker for the ALT pathway for diagnostic, prognostic, and, potentially, therapeutic purposes." (PMID 30226859, 2018). "In summary, we describe, for the first time, the epigenomic consequences of ATRX deficiency in putative glioma cells of origin, along with their effects on gene expression programs and cellular differentiation and motility phenotypes." (PMID 29535300, 2018). "We investigated expression of ATRX, since in gliomas loss of ATRX can be found in IDH mutant tumours." (PMID 28484589, 2017). "He then shared several case studies on ATRX/DAXX mutations in glioma molecular classification and subsequent treatment." (PMID 28797870, 2017). "Classified as a tumor suppressor gene, ATRX is frequently mutated in neuronal-related cancers, such as neuroendocrine cancers, gliomas, and neuroblastoma, and more recently also in an aggressive form of smooth muscle tumors." (PMID 28423598, 2017). "In contrast to IDH1-mutant gliomas, ATRX mutations associated with H3G34V, ZMYND11, EP300, or BRAF V600E were stable across the disease course in our study." (PMID 29084603, 2017). "We conclude by discussing some of the challenges associated with incorporating ATRX status assessment into routine clinical practice while also exploring opportunities for future diagnostics/therapeutics in gliomas based on ATRX status." (PMID 29034211, 2017). "Some molecular genetic features including IDH1/2 mutation, MGMT promotor methylation, codeletion of 1p/19q, TERT loss, and ATRX mutation have been reported to be associated with favorable prognosis in gliomas." (PMID 29110682, 2017). "Overall, these studies highlight some important characteristics of ATRX mutations within gliomas that will aid in their detection." (PMID 29034211, 2017). "For example, the ATRX gene frequently harbours NMD-elicit mutations in low grade glioma and sarcoma." (PMID 28649990, 2017). "Since in gliomas loss of the chromatin remodeler ATRX can be found in IDH mutant tumours, we evaluated a possible co-occurrence in chondrosarcoma." (PMID 28484589, 2017). "ATRX inactivation within gliomas can be due to mutations, deletions, gene fusions, or an amalgam of these causes." (PMID 29034211, 2017).
glioma (continued). "In order to interrogate if ATRX or an ATRX mutant (R1426*) that is present in gliomas affect DAXX-PTEN and/or DAXX-H3.3 association we overexpressed these constructs and analysed their effect." (PMID 28497778, 2017). "ATRX mutations were found to be restricted to IDH1/2 mutated glioma tumors and were also associated with better prognosis." (PMID 27698411, 2016). "It has been reported that many TERT wild-type gliomas harbor highly frequent ATRX mutations, which induce the Alternative Lengthening of Telomeres (ALT) phenotype." (PMID 26556853, 2016). "These criteria, which set a stringent level (at least > 55% of tumor cells) for the definition of the 1p/19q codeletion by FISH, identified all IDH1/2 mutated and ATRX wild type gliomas that meet the 2016 WHO Criteria for OGs." (PMID 28030632, 2016). "Recently, several teams demonstrated that IDH mutations and ATRX status, combined with other classical biomarkers, refined the molecular classification of adult gliomas, providing a prognostic tool for clinicians." (PMID 27713914, 2016). "We also found that loss of ATRX caused by siRNA induced apoptotic cells increasing, reduced tumor cell proliferation and repressed the cell migration in glioma cells." (PMID 25971279, 2015). "And we also found that loss of ATRX caused by siRNA induced apoptotic cells increasing, reduced tumor cell proliferation and repressed the cell migration in glioma cells." (PMID 25971279, 2015). "For example, the mutational load of ATRX mutated gliomas increased from 21.6 ± 10.3 and 26.0 ± 11.2 to 65.4 ± 40.1 mutations per sample (P < 0.0001) for grade II, III and IV gliomas respectively." (PMID 26699864, 2015). "Mutations that inactivate ATRX gene are common in human pancreatic neuroendocrine tumors and central nervous system tumors." (PMID 26448930, 2015). "Recently, mutations of the ATRX gene have been found in various subtypes and grades of gliomas and were shown to refine the prognosis of malignant gliomas in combination with IDH and 1p/19q status." (PMID 24559763, 2014). "Recently, mutations in the ATRX (α-thalassemia/mental retardation syndrome X-linked) gene have been detected in gliomas of various subtypes and grades." (PMID 24559763, 2014). "Analyses of ATRX in a series of 363 gliomas of various subtypes and grades revealed mutations in 25.6% of all tumors." (PMID 24559763, 2014). "In summary, our findings both identify ATRX mutation as a defining molecular determinant for a large subset of IDH-mutant gliomas and have direct implications on pathogenic mechanisms across the wide spectrum of LGGs." (PMID 23104868, 2012). "We recommend routine H3K27M testing in IDH-wildtype hemispheric gliomas with ATRX loss." (PMID 42117138, 2026). "Similarly, SIRT2 inhibitors have shown promise in targeting ATRX (alpha-thalassemia mental retardation X-linked)-deficient gliomas, highlighting its role in driving oncogenic phenotypes in specific tumor subtypes." (PMID 40710366, 2025). "Notably, loss of ATRX expression has been identified as a poor prognostic marker in other malignancies, such as glioblastoma multiforme and low-grade gliomas." (PMID 41228336, 2025).
glioma (continued). "Notably, a previous study reported that gliomas with ATRX mutations are more likely to be infiltrated by immunosuppressive monocytic-lineage cells derived from circulation." (PMID 40495762, 2025). "For example, an magnetic resonance imaging-based study might be considered, to assess hypoxia in ATRX-deficient glioma." (PMID 39921567, 2025). "Importantly, SETD2 CNV loss was significantly more common in ATRX-mutant glioma (14.4%) as compared to ATRX-wildtype glioma (7.9%)." (PMID 39921567, 2025). "ATRX mutations can be used as prognostic indicators in patients with glioma." (PMID 40103938, 2025). "The results showed that the proportion of IDHR132H+ tumor cells in IDH‐mutated gliomas was significantly higher than that in the wild‐type group, and the proportion of ATRX+ tumor cells in ATRX‐mutated gliomas was significantly lower than that in the wild‐type group." (PMID 40264576, 2025). "ATRX is a chromatin remodeler with high mutation frequency in glioma." (PMID 40523311, 2025). "Importantly, in gliomas, ATRX loss (detected by immunohistochemistry) is a diagnostic criterion for grade 2 to 4 IDH-mutant astrocytomas, which represent 20–25% of diffuse gliomas." (PMID 41422096, 2025). "In IDH1/2-mutant gliomas, elevated TERTp mutation rates predominantly reflected oligodendroglioma molecular profiles (with 1p/19q co-deletion), whereas astrocytoma subtypes were characterized by higher ATRX mutation rates." (PMID 41377022, 2025). "Importantly, these cohorts include gliomas beyond astrocytomas, covering the full spectrum of contexts in which ATRX mutations occur." (PMID 41422096, 2025). "Other pathways may drive ALT formation in various glioma types, but the mechanism linking ATRX loss to ALT remains to be further explored." (PMID 39479502, 2024). "Moreover, mice harboring ATRX-deficient gliomas in the context of our RCAS/Ntv-a genetically engineered model also exhibited extended survival relative to ATRX-intact counterparts, in both de novo and re-injection contexts." (PMID 38272925, 2024). "The present study demonstrated that the ATRX mutation rate in patients with GBM was significantly lower than that in patients with low-grade glioma, and that patients harboring an ATRX mutation exhibited a prolonged survival, compared with to those harboring the wild-type gene." (PMID 38898533, 2024). "Loss of ATRX has also been shown to augment the ability of glioma cells to induce T-cell apoptosis." (PMID 38898533, 2024). "H3.3-altered gliomas may also have mutually exclusive alterations in ATRX or TOP3A implicated in the Alternative Lengthening of Telomeres phenotype." (PMID 39126064, 2024). "This strategy yielded ATRX-intact and deficient gliomas that could then be subjected to ex vivo culture as well as serial transplantation." (PMID 38272925, 2024). "Interestingly, IDH mutations, which almost invariably arise with ATRX mutations in adult gliomas, have been shown to suppress leukocyte chemotaxis and infiltration." (PMID 38272925, 2024). "In this way, the precise timing and order of mutational acquisition could significantly impact therapeutically tractable sensitivities conferred by ATRX deficiency in glioma cells." (PMID 38272925, 2024). "Loss of ATRX was identified in 11.9% of cases, compared to 15.3% in another study, and has been significantly associated with better overall survival in high-grade glioma patients." (PMID 38633919, 2024).
glioma (continued). "Genetic characteristics of ATRX-deficient IDH-wildtype adult high-grade gliomas suggest that these tumors are particularly intriguing targets of potential future therapeutic interventions including immunotherapies combined with MAPK pathway inhibition and DNA repair inhibitors." (PMID 37891325, 2023). "Besides, we also found that IDH1 and ATRX mutations, as representative molecular features of gliomas, had a high frequency in each group." (PMID 37488496, 2023). "ATRX mutation is observed in various gliomas, particularly in low‐grade gliomas with IDH mutation." (PMID 37311690, 2023). "Moreover, the presence of a TERT promoter mutation was evaluated, with the usually mutually exclusive presence of TERT promoter mutations and ATRX mutations described in gliomas as well as cutaneous melanomas." (PMID 37629169, 2023). "Additionally, loss of ATRX induces an immunosuppressive microenvironment in gliomas by promoting the secretion of immunosuppressive cytokines and upregulating the expression of immune checkpoint molecules, suppressing anti‐tumor immunity." (PMID 37311690, 2023). "Co-mutation between IDH1 and ATRX is well described in gliomas." (PMID 36883553, 2023). "Although the relevance of these non-BRCA gene mutations in the effects PARP inhibitors is not completely clarified, their synchronous presence with ATRX loss raises the possibility that ATRX-deficient high-grade gliomas are promising targets of PARP inhibitors." (PMID 37891325, 2023). "Though ATRX was originally discovered as the cause of the α-thalassemia, mental retardation, and X-linked (ATRX) syndrome, to date mounting evidence suggests that ATRX is mutated in a wide range of cancers, including gliomas, neuroblastomas, and sarcomas." (PMID 37046839, 2023). "Interestingly, AYA gliomas had more mutations in ATRX (41.3% vs. 12.5%), a chromatin regulator previously associated with Alternative Lengthening of Telomeres26 (ALT), a telomere maintenance pathway complementary to active telomerase." (PMID 36433963, 2022). "ATRX deficiency is correlated with poor survival prognosis of glioma patients." (PMID 36468012, 2022). "Furthermore, ATRX mutations are also significantly associated with IDH mutations in glioma patients." (PMID 36292695, 2022). "Furthermore, we demonstrate that a combinatorial treatment of RTKi with temozolomide (TMZ)–the current standard of care treatment for GBM patients–causes pronounced toxicity in ATRX-deficient high-grade glioma cells." (PMID 35406561, 2022). "Indeed, the mutations identified in the patient-derived glioma cells used in this study (U3129 and U3034) are intronic and missense mutations that lead to reduced ATRX levels." (PMID 35406561, 2022). "Given the high prevalence of ATRX mutations in cancer, particularly in gliomas, identifying drugs highly toxic for ATRX-deficient cells may lead to clinical applications." (PMID 35406561, 2022). "This may suggest a direct or indirect compensatory relationship between these two events, which may explain the higher toxicity of PDGFRi in ATRX-deficient high-grade glioma cells." (PMID 35406561, 2022). "Our findings suggest that combinatorial treatments with TMZ and RTKi may increase the therapeutic window of opportunity in patients who suffer high-grade gliomas with ATRX mutations." (PMID 35406561, 2022).